LY6K (lymphocyte antigen 6 family member K)
Diseases named in the same sentence as LY6K in open-access papers (continued):
Sharing a sentence is not in itself a finding about the gene and the disease.
kidney cancer (1 paper, 2016). Primary or metastatic malignant neoplasm involving the kidney. "High Ly6K mRNA expression in kidney cancer was significantly correlated with decreased one-year overall survival (dead, n=16 vs alive, n=55) and five-year overall survival (dead, n=12 vs alive, n=9) in Zhao and TCGA studies respectively." (PMID 26862846, 2016).
male infertility (1 paper, 2018). The inability of the male to effect fertilization of an ovum after a specified period of unprotected intercourse. "Genetic loss of Ly6K in mice impairs sperm transit into the oviduct, resulting in male infertility." (PMID 29342175, 2018).
mastitis (1 paper, 2019). Inflammation of breast tissue during lactation or postpartum due to an obstructed duct or infection. "The putative role of these two genes (LY6H and LY6K) in immune response has been reported in several previous investigations and LY6K gene was reported to be a significant candidate gene for mastitis susceptibility in US and Chinese Holstein cattle." (PMID 31311492, 2019).
pancreatic cancers (1 paper, 2016). "The mRNA expression data across multiple studies shows that ovarian, colorectal, gastric, breast, lung, brain and CNS, cervical, esophageal, head and neck and pancreatic cancers express significant high levels of Ly6D, Ly6E, Ly6H, Ly6K." (PMID 26862846, 2016).
prostate carcinoma (1 paper, 2016). A carcinoma that arises from epithelial cells of the prostate gland. "This analysis showed that four different members Ly6D, Ly6E, Ly6H or Ly6K have increased gene expressed in bladder, brain and CNS, breast, colorectal, cervical, ovarian, lung, head and neck, pancreatic and prostate cancer than their normal counter part tissues." (PMID 26862846, 2016).
tongue cancer (1 paper, 2025). A malignant neoplasm affecting the tongue. "Among these, four genes (LY6K, ATAD2, CEP55, and MAGEA3) emerged as the most predictive of nodal spread specifically in tongue cancer." (PMID 41009820, 2025).
uterine tumor (1 paper, 2023). "If this mRNA is being translated to yield high levels of LY6K on the surface of uterine tumor cells, then cell-based therapies against LY6K might be able to selectively target and kill these cancer cells." (PMID 37141412, 2023).
cancer (48 papers, 2011 to 2025). A tumor composed of atypical neoplastic, often pleomorphic cells that invade other tissues. "Other novel mRNAs/proteins that were upregulated in this population included LY6K, which marks the progression of many cancers and has been implicated in immune escape." (PMID 34557907, 2021). "As the normal function of LY6K is limited to normal testis, it is reasonable to anticipate limited toxicity associated with LY6K-targeted cancer treatment." (PMID 32098321, 2020). "Small molecule NSC243928, an anti-cancer agent, showed the highest loss in cell death activity in the LY6K knockdown cells." (PMID 32098321, 2020). "One confirmed target of mivaRNA is the protein Ly6K (lymphocyte antigen 6 complex, Locus K), a protein associated with cell growth and implicated in several cancers such as lung, breast or head and neck." (PMID 28769895, 2017). "The Ly6K and Ly6E proteins are implicated as cancer vaccine targets and drug conjugated antibody therapy, respectively suggesting that Ly6 family members can be used as novel candidates to develop targeted therapies." (PMID 26862846, 2016). "Besides LY6A/LY6S, other LY6 family members have been suggested as close homologues of the murine Ly6a gene, such as LY6D, LY6E, LY6H and LY6K, which were implicated as biomarkers for poor cancer prognosis and are frequently amplified in human cancer." (PMID 39642167, 2025). "LY6K plays a role in cancer, and contributes to sperm function in mice, which however do not have this ERV-V promoter." (PMID 40083010, 2025). "Meanwhile, LY6K has been shown to be critical for cancer cells’ ability to evade immune surveillance." (PMID 39727968, 2024). "LY6K has also been explored as a target for cancer immunotherapies such as vaccines and T-cell-based therapies." (PMID 39727968, 2024). "Large-scale clinical trials are also necessary to validate LY6K as a safe and effective target across different cancer types." (PMID 39727968, 2024). "Among the Ly6/uPAR members, LY6K (also named cancer-testis antigen) has been identified as a putative oncogene with elevated expression in several cancers, such as breast, head-and-neck, bladder, lung, and eraesophageal cancers." (PMID 39727968, 2024). "Lymphocyte antigen 6 complex locus K (LY6K), a glycosylphosphatidylinositol‐anchored protein, plays a dynamic role in cancer metastasis." (PMID 37076981, 2023). "The human LY6 family of proteins including LY6K reside in the syntenic area of chromosome 8, and they are upregulated in many types of human cancers, including, breast, brain, lung, ovarian, bladder, kidney, and head and neck cancer." (PMID 37628960, 2023). "While this manuscript was in progress we were happy to see that LY6K and TbR1 interacted in cancer cells." (PMID 37628960, 2023). "LY6K‐depletion in HeLa and SiHa cancer cells suppressed EGF‐induced proliferation and TGF‐β‐enhanced migration and invasion." (PMID 37076981, 2023). "We have discovered that a small molecule binder of LY6K can inhibit LY6K-signaling, reduce tumor growth, and induce an anti-cancer immune response in vivo." (PMID 37628960, 2023). "Analysis of the TCGA and GTEx dataset were performed to explore the expression and survival of LY6K in cancer patients." (PMID 37076981, 2023). "Since TGF‐β and EGF signals regulate tumor initiation and metastasis, elucidating LY6K expression during cancer progression is important." (PMID 37076981, 2023). "Future studies should focus on strategies to disrupt the LY6K-TGF-β receptor complex to attenuate this signaling in cancer cells." (PMID 37628960, 2023). "High LY6K expression is associated with poor prognosis and survival outcomes in various cancer types, and LY6K inhibition suppresses cell growth of cancers." (PMID 34980214, 2022). "Elevating LY6K expression notably promoted the migration and invasion of cancer cells, however co-transfection of miR-324-3p mimic and pcDNA-LY6K ameliorated the impact." (PMID 34980214, 2022).
cancer (continued). "This study sets up the groundwork to discover novel drugs targeting LY6K to treat cancers with high LY6K expression." (PMID 32098321, 2020). "MiR‐500a‐3p has been reported to be involved in the chemoresistance, invasion and migration via GSK‐3β and LY6K in different types of cancers." (PMID 32588541, 2020). "The shRNA-mediated LY6K knockdown in cancer cells results in reduced tumor growth for in vivo tumor models." (PMID 32098321, 2020). "We envision that LY6K is an ideal target for drug development for women’s cancer since the molecule’s normal expression is limited to the testis." (PMID 32098321, 2020). "cBioPortal was used to visualize LY6K mRNA expression in The Cancer Genome Atlas (TCGA) pan-cancer datasets." (PMID 32098321, 2020). "Our data demonstrate a first-time proof of principle study that pharmacological inhibition of LY6K using small molecules in cancer cells is a valid approach to developing targeted therapies against LY6K." (PMID 32098321, 2020). "More work is needed to understand how LY6K can be used as a potential therapeutic target for precision medicine cancer treatment, using this new biomarker to design more effective treatment plans." (PMID 32098321, 2020). "LY6K is a highly specific target as it is a cancer-testis antigen expressed exclusively in normal reproductive tissues and also in some cancer cells." (PMID 30655605, 2019). "The human LY6K gene is aberrantly expressed in various carcinomas and has been identified as a target antigen for diagnosis and cancer vaccine therapies." (PMID 27494879, 2016). "Our data suggested that methylation pattern of LY6K is useful biomarker of cancer because LY6K expression was cancer-specifically decreased by CGI shore methylation." (PMID 27494879, 2016). "Since overexpression of LY6K was correlated with poor prognosis for patients with these carcinomas, this molecule is thought to possess biological functions such as cancer cell differentiation, proliferation, adhesion, and migration." (PMID 27005865, 2016). "The CpG site within the closed chromatin region showed a hypermethylated pattern, suggesting that LY6K gene expression in cancer can be predicted using DNA methylation status and a chromatin mark in the functional 5′CGI shore of LY6K." (PMID 27494879, 2016). "On the other hand, hypomethylation of oncogenes, such as retinoblastoma binding protein 6 (RBBP6), solute carrier family 34 member 2 (SLC34A2), and lymphocyte antigen 6 complex locus K (LY6K), is frequently observed in numerous cancers, facilitating aberrant gene activation." (PMID 40663150, 2025). "Thus, LY6K is a valid target for developing therapeutic strategies to inhibit TGF-β signaling in cancer cells." (PMID 37628960, 2023). "The structural insight into the LY6K-TbR1 interaction may shed light on strategies for disrupting TGF-β signaling in cancer cells expressing LY6K." (PMID 37628960, 2023). "Additionally, LY6K is also expressed in human cancer cells and is, therefore, one of the cancer/testis antigens (CTA)." (PMID 37076981, 2023). "However, up-regulation of miR-324-3p neutralized the cancer-promoting effect induced by LY6K overexpression." (PMID 34980214, 2022). "LY6K is reported to be the target gene for miR-324-3p and that LY6K functions in several cancers." (PMID 34980214, 2022). "In the future, pharmacological inhibition of LY6K may be a viable option for novel cancer treatment." (PMID 32098321, 2020). "Since inhibition of LY6K expression inhibits cancer cell growth, we set out to explore whether pharmacological inhibition of LY6K could produce the same effect." (PMID 32098321, 2020). "It remains to be seen if LY6K is more active in stem-like cancer cells." (PMID 32098321, 2020). "Increased expression of Ly6D, Ly6E, Ly6H or Ly6K was observed in sub-set of cancer type." (PMID 26862846, 2016). "We investigated whether Ly6K was differentially expressed in clinical samples of cancer in multiple studies." (PMID 26862846, 2016).
cancer (continued). "Lymphocyte antigen 6K (LY6K), cell division cycle-associated protein 1 (CDCA1) and insulin-like growth factor 2 mRNA-binding protein 3 (IMP3) were identified through genome-wide microarray analysis of various cancer tissues and investigated by a Japanese research team." (PMID 32942747, 2020). "Following the confirmation of EMT in EC, TTK, LY6K, and NOL4 have recently been reported as cancer-testis antigens with a bad prognosis, with TTK being particularly overexpressed in early-stage cancer." (PMID 41312167, 2025). "Computational analysis initially identified 40 cancer-active CTA genes, of which four genes (LY6K, MAGEA3, CEP55, and ATAD2) were most indicative of nodal spread." (PMID 41009820, 2025). "LY6/uPAR superfamily members, such as LY6E, LY6H, LY6K, and PSCA, are overexpressed in various cancers and contribute to tumor growth, invasion, and metastasis." (PMID 39727968, 2024). "We found that except LY6K and MDGA2, all other hub genes were differentially expressed between PCa tissues and para-carcinoma tissues." (PMID 35780240, 2022). "Cancer vaccines containing a combination of multiple peptides derived from TTK, lymphocyte antigen 6 complex locus K (LY6K), and insulin-like growth factor-II mRNA binding protein 3 (IMP3) were tested in phase II clinical trials for treatment of advanced EC." (PMID 34513829, 2021). "Interestingly, Ly6K is a 'cancer-testis antigen' expressed at elevated levels in various cancers, and a promising target for anticancer vaccine production, thus establishing its general suitability as a vaccine antigen that might also prove useful in an immunocontraceptive formulation." (PMID 29342175, 2018). "Therefore, targeting LY6K epigenetic modification may be a useful cancer therapeutic strategy." (PMID 27494879, 2016). "LY6K is a highly cancer-specific protein, and it is not expressed in normal organs except in the testes." (PMID 37628960, 2023). "The data presented in this report elaborate on amino acid residues in LY6K, which may interact with TbR1 to modulate the TGF-β receptor complex in cancer cells and affect the tumor microenvironment." (PMID 37628960, 2023). "We discovered that increased expression of LY6K in cancer cells led to increased TGF-β signaling and that inhibition of LY6K could lead to reduced TGF-β signaling and reduced in vivo tumor growth." (PMID 37628960, 2023). "Both TEX101 and LY6K are known to be soluble in serum, an important characteristic shared with several other GPI-APs that are already useful biomarkers for various cancer types." (PMID 35774118, 2022). "Indeed, we have examined several peptides derived from a variety of cancer-testis antigens that have the oncogenic activity, including KIF20A, DEPDC1, MPHOSPH1, URLC10(LY6K),TTK, KOC1(IMP3), CDCA1, RNF43, and TOMM34." (PMID 24237633, 2013).
tumor (25 papers, 2011 to 2025). "LY6K overexpression has been linked to tumor progression, metastasis, and poor prognosis, thus making it a potential diagnostic or prognostic biomarker." (PMID 39727968, 2024). "We observed that the downregulation of LY6K using shRNA can reduce in vivo tumor growth via signaling pathways associated with immune pathways." (PMID 36900259, 2023). "Increased expression of LY6K is also associated with increased TGFβ signaling and tumor growth in vivo." (PMID 32098321, 2020). "This locus is amplified frequently in multiple human tumor types including those of the bladder and prostate Lymphocyte antigen 6 family member K (LY6K) is a gene associated with cell growth and is upregulated in human cell lines displaying 8q24.3 amplification." (PMID 32209086, 2020). "A LY6K-derived polypeptide vaccine has shown promising results in clinical trials, demonstrating the ability to induce effective immune responses, suppress tumor growth, and improve prognosis in patients with advanced solid tumors." (PMID 39727968, 2024). "Regular measurements of tumor volume showed that LY6K silencing significantly decreased the tumor growth rate compared to the scrambled control (p < 0.0001)." (PMID 39727968, 2024). "Reduced production of the Ly6D and Ly6K proteins was shown after ASPH inhibition in human tumor cell lines." (PMID 38356711, 2024). "In our previous studies, proteins from the Ly6 family, LY6D, have been identified to be upregulated in colon CSCs, where they are implicated in tumor progression and CSC maintenance, while research on LY6K in colon CSCs is limited." (PMID 39727968, 2024). "LY6K also promotes drug resistance and epithelial-to-mesenchymal transition that contribute to tumor growth." (PMID 39727968, 2024). "These include optimizing delivery methods for LY6K-targetd therapies, ensuring immune responses are specific and durable, and avoiding immune evasion by tumor cells." (PMID 39727968, 2024). "To extend our findings to human cells, we tested the levels of Ly6D and Ly6K proteins, which are upregulated in various tumor types 53, in 5 human tumor cell lines (HeLa, SiHa, CaSki, Detroit 562, and MCF-7) and showed their reduction after ASPH inhibition." (PMID 38356711, 2024). "In an exploratory analysis, expression of KIF20A, CT45, and LY6K as measured by IHC was correlated to clinical features to identify a potential prognostic or tumor biological relevance of the TAA in EOC." (PMID 36768616, 2023). "LY6K has also been reported to suppress tumor immunity by increasing tumor‐infiltrating T regulatory cell numbers and decreasing natural killer (NK) cell activation." (PMID 37076981, 2023). "A total of 28 LY6K-positive samples showed a 100 percent staining, and only 5 were positive in fewer than 50 percent of the tumor cells." (PMID 36768616, 2023). "Our mined transcriptomic information indicates that LY6K mRNA is significantly upregulated (>8 fold) in UCEC patient tumor tissues." (PMID 37141412, 2023). "Finally, the quantification of two members of the Ly6 family - Ly6D and Ly6K - was performed in 5 human tumor cell lines." (PMID 38356711, 2024). "In vivo, LY6K silencing effectively reduced tumor growth and extended survival in a mouse model." (PMID 39727968, 2024). "Furthermore, xenograft tumor volumes from LY6K knockdown nude mice were reduced than those of mice treated with control lentivirus." (PMID 27494879, 2016). "In addition, knockdown of LY6K delayed tumor progression in secondary xenograft tumors." (PMID 27494879, 2016). "In addition, knockdown of LY6K delayed tumor progression in xenograft tumors." (PMID 27494879, 2016). "Mechanistically, LY6K activates the ERK-AKT and TGF-β pathways, which are critical for tumor cell proliferation, migration, invasion, and metastatic spread." (PMID 41009820, 2025).
tumor (continued). "A study revealed that the increased expression of Ly6K/E promotes cytokine-induced immune checkpoint molecules PDL1 and CTLA4 expression, enhances tumor-infiltrating T regulatory cells, and reduces natural killer cell activation." (PMID 39727968, 2024). "Thus, we wanted to see whether a pharmacological agent that binds with LY6K to induce cell death in vitro could also inhibit tumor cell growth in vivo, and whether this inhibition is accompanied by changes in the tumor microenvironment in the context of immune cell infiltration." (PMID 36900259, 2023). "In this study, we report that LY6K‐depletion suppresses the effect of TGF‐β on invasiveness and EGF‐stimulated proliferation of tumor cells by repressing clathrin‐ and CAV‐1‐mediated endocytosis." (PMID 37076981, 2023). "All LY6K-specific CTL clones showed Ca2+ influx, IFN-γ production and cytotoxicity when co-cultured with LY6K-pulsed tumour cells, indicating that CTA peptide-based vaccination induces antigen-specific CTLs." (PMID 35574342, 2022). "LOC100363492 (Ly6k), MGC114427 (Magea9), and Mageb1 are known as tumor antigens and were all expressed at a lower level in MLL- than in AT1-tumors, especially Ly6k." (PMID 28472073, 2017). "LY6K may modulate the transition of TGF-β signaling from a suppressive to a promotive role, enhancing tumor progression and altering the cell cycle." (PMID 39727968, 2024). "LY6K immunohistochemical analysis using 144 clinical samples indicated that LY6K mainly localized in the cell membrane and cytoplasm of the tumor cells, while peri-tumoral stromal tissue did not expressed LY6K." (PMID 27494879, 2016). "Interestingly, our data on exosomal protein profiles from treated Caco-2 showed an enrichment of upregulated proteins involved in tumor etiopathogenesis, including CRC (CD59, CRP, CTSD, HMMR, LY6K, TRIM22), and in cell cycle control (BRAF, CDC2, ERBB2)." (PMID 25594007, 2014). "Heat shock-activated HSF1 is mainly responsive to the expression of heat shock proteins, while activation of HSF1 in tumor tissues is predominantly responsible for controlling the expression of non-heat shock proteins, e.g. CKS2, LY6K, RBM23, CCT6A, CKS1B, ST13 and EIF4A2." (PMID 25199534, 2014).
LY6K also shares sentences with these, for which no sentence is quoted: head and neck squamous cell carcinoma (4 papers); malignant glioma (2); adenocarcinoma (1); breast tumor (1); hypertriglyceridemia (1); metastatic tumors (1); Palmoplantar keratoderma (1); pituitary tumor (1).